MUC4 (mucin 4, cell surface associated)
Diseases named in the same sentence as MUC4 in open-access papers (continued):
Sharing a sentence is not in itself a finding about the gene and the disease.
cancer (continued). "In the present report, we analyzed MUC4 expression systematically in all organs and confirmed its aberrant expression in associated carcinoma." (PMID 30236127, 2018). "We analyzed MUC4 expression systematically in all organs in TCGA and CCLE large scale databases and confirmed its aberrant expression in associated carcinoma and the MUC4 impact on patient’s survival." (PMID 30236127, 2018). "MUC4 expression is associated with the malignant transformation of ovarian epithelial cells into cancer cells." (PMID 27829225, 2017). "MUC4 is a high-molecular weight glycoprotein that has been implicated in cancer progression particularly due to its cell signaling and anti-adhesive properties." (PMID 27519953, 2016). "Several proteins involved in cancer pathways had mutations in more than one patient, the most common being MUC4, GOLGA6L2, DSPP, FOXO6 and HLA-DRB1." (PMID 25605237, 2015). "Enrichment analysis with KEGG confirmed that the set of 1575 DEGs was enriched for pathways not only correlated to cancer, but also were associated with MUC4, as shown in the literature database, and was consistent with the GO functional enrichment analysis." (PMID 25367394, 2014). "Galectins, lectins that are known to interact with mucins and alter cancer cell properties, were found to be down-regulated in MUC4 deficient cells (galectin-1)." (PMID 22393391, 2012). "Mucin 4 (MUC4) is a high molecular weight transmembrane mucin that is overexpressed in many carcinomas and is a risk factor associated with a poor prognosis." (PMID 19127263, 2009). "In the four series, survival in MUC4-positive or high-expression cases was significantly worse than that for MUC4-negative or low-expression cases, and multivariate analyses showed that MUC4 expression in the carcinomas was a risk factor for a poor prognosis." (PMID 19127263, 2009). "MUC4 is a large, heavily glycosylated transmembrane mucin, that is implicated in the pathogenesis of various types of cancers." (PMID 18781152, 2008). "We found a significantly lower expression of MUC4 in dysplastic and cancer tissue, suggesting that progressive loss of MUC4 may be implicated in the development of CAC." (PMID 38505585, 2024). "MUC4 is frequently linked to cancer and is known to contribute to development and aggressiveness." (PMID 38156143, 2023). "Moreover, because MSI is closely related to CRC and MSI-high status is an emerging predictive and prognostic biomarker for the immunotherapy response in cancer, we measured the associations of MUC4 polymorphisms with MSI status." (PMID 37384668, 2023). "The underlying characteristics of MUC4 in diverse cancer types may enable us to provide suitable treatment and patient monitoring." (PMID 38156143, 2023). "With detecting of peripheral blood samples in metastatic epithelial cancer, a recent study has demonstrated that mutations in the MUC4 antigen can be recognized by memory T cells, indicating the existence of somatic mutations in the MUC4 antigen during cancer progression." (PMID 33714943, 2021). "The underlying features of MUC4 across various cancer types may allow us to ensure appropriate treatment and patient monitoring." (PMID 34336844, 2021). "MUC4 plays an important role as a potential candidate for diagnostic and treatment in cancer." (PMID 33431054, 2021). "To identify the mechanism by which MUC4 impacts survival, we used cBioPortal to explore alteration frequencies, including mutation, fusion, amplification, deep deletion, and multiple alterations, of MUC4 in different cancer types." (PMID 34336844, 2021).
cancer (continued). "We tested whether the 10 rare variants of MUC4 gene were related to cancer using germline variants from blood in the Cancer Genome Atlas Study data." (PMID 32701958, 2020). "Moreover, MUC4 itself also modulates cell apoptosis, regulates cell–cell adhesion, and serves as a tumour-associated target for cancer therapy." (PMID 31514468, 2019). "Our results suggested recurrent mutations of MUC family genes are closely associated with survival in diverse cancers, so the mutations of MUC4 may cause the increase in mRNA expression and further protect epithelial surfaces in ESCA and STAD." (PMID 30107644, 2018). "MUC4 may therefore be a useful prognostic and diagnostic tool that improves our ability to eradicate various forms of cancer." (PMID 27829225, 2017). "MUC4 associates with poor prognosis in several cancer types and may serve as a potential marker for pancreatic cancer." (PMID 28978023, 2017). "In addition, MUC4 has also been implicated in cancer by mediating the epidermal growth factor family of enzymes, including the tyrosine kinase receptor ERBB2." (PMID 26686060, 2015). "An understanding of epigenetic changes in MUC4 may contribute to the diagnosis of carcinogenic risk and prediction of outcome in patients with cancer." (PMID 19127263, 2009). "MUC4 expression in a variety of cancer is associated with poor prognosis." (PMID 17595659, 2007). "One of the top recurrently mutated cancer genes identified from mapping to CanFam4 was MUC4; however, only some of these variants could be validated via Sanger sequencing due to the highly repetitive sequence of the MUC4 gene." (PMID 41353477, 2025). "Moreover, MUC4 expression has been linked to the metastatic potential of the cancer cells." (PMID 37284199, 2023). "Similarly to MUC1, MUC4 is a factor associated with poor prognosis in several carcinomas, and thus we hypothesised that MUC4 is also regulated by an epigenetic mechanism." (PMID 19127263, 2009). "High expression levels of ErbB and its ligands in the TME correlate with enhanced cancer aggressiveness, highlighting the importance of MUC4’s role in the modulation of this signaling axis." (PMID 40655139, 2025). "Using the Cancer Genome Interpreter, we identified five recurrent cancer driver mutations spanning MUC16, MUC4, ALK, and CTNND1, with the latter being novel and containing a missense mutation, R439C." (PMID 39338204, 2024). "According to the list of the top 10 most frequently mutated genes, MUC4, MUC16, KMT2C, and PREX2 were annotated as cancer driver genes." (PMID 39338204, 2024). "Our study is the first in Thai patients to draw a comprehensive mutational landscape of somatic mutations and identify frequently mutated genes, such as MUC4 and MUC16, with significant cancer driver alterations." (PMID 39338204, 2024). "In the present study, although all four cases were classified as low-grade carcinomas according to Ellis and Auclair’s methods, only case three was MUC4 positive in immunohistochemical staining." (PMID 38243319, 2024). "Galectin-3 can also bind to hnRNP L to stabilize the mucin MUC4 mRNA in the cytoplasm of cancer cells." (PMID 36823664, 2023). "It is noteworthy that Muc4, an oncogene in tier-2 genes in the Cancer Gene Census, had frameshift indels on chromosome 16." (PMID 37367035, 2023). "MUC4 expression was reported to be higher in various cancer types such as breast, pancreatic, lung, ovarian, bladder and cervical cancer." (PMID 37284199, 2023). "Both MUC4 and the proliferation marker Ki-67 had the highest expression in superficial cancer compared with the other tissues; as well, Ki-67 expression in deep cancer was higher than in non-neoplastic epithelium." (PMID 37674528, 2023). "In published single sequencing data from human subjects, MUC4 expression was greatest in pit cells from subjects with metaplasia and cancer." (PMID 37674528, 2023).
cancer (continued). "It is evident from the volcano plot that highly mutated genes MUC4, MUC16, CIITA, and ALK are mutated and overexpressed, of which ALK and CIITA are cancer census genes, whereas NCOR2 a transcriptional corepressor was mutated and downregulated." (PMID 37091785, 2023). "Although many other cancer-related genes showed a high frequency of mutations in OS, the MUC family of genes (MUC6, MUC12, and MUC4) were found to be highly mutated in our study." (PMID 37046795, 2023). "MUC4 is a member of the transmembrane mucin family, and aberrant expression has been reported in a variety of carcinomas." (PMID 37367035, 2023). "Cancer studies show that MUC4 is aberrantly expressed in various malignancies and validate MUC4 as a novel target for cancer diagnosis." (PMID 35741699, 2022). "In GBM cases displaying the highest MUC4 expression, MUC4 was prominently expressed in cancer cells." (PMID 36400876, 2022). "In GBM patients expressing MUC4, the protein was found in the cytoplasm of cancer cells, in a manner similar to EGFR." (PMID 36400876, 2022). "Despite MUC4′s enormous pathological importance in various cancers, A. muricata’s high therapeutic suitability for various tumors, especially PC, is indicated by MUC4 down-regulation." (PMID 36139697, 2022). "On the other hand, the expression of MUC3 and MUC4 was significantly reduced as the cancer stage increased." (PMID 35038288, 2022). "A recent study found that MUC4, a regulator of cell apoptosis and tumorigenesis, is aberrantly expressed in numerous cancer types." (PMID 36142830, 2022). "Muc4 maintains the intestinal homeostasis by upregulation of Muc2 and Fam3D (guardians of the gut) and downregulation of cancer-promoting mucin (Muc13)." (PMID 35255004, 2022). "To characterize the functional roles of MUC4 in cell proliferation, we calculated the Rs between MUC4 and the well-known proliferation marker ki67 across cancer types." (PMID 34336844, 2021). "To address this issue, we performed an integrative analysis about MUC4 to understand its effect on survival and immunomodulation, which is necessary to develop the MUC4-based cancer therapy." (PMID 34336844, 2021). "We previously showed NF-κB subunit accumulation in the cytoplasmic fraction of MUC4-KD cancer cells." (PMID 34944818, 2021). "We have previously cloned MUC4 “minigene” containing all the MUC4 domains but only 10% of the TR domain and used it to discern the functional role of MUC4 in cancer cell lines using overexpression studies." (PMID 34887447, 2021). "Overall, these findings strongly suggest that MUC4 can serve as a prognostic biomarker in pan-cancer." (PMID 34336844, 2021). "Our results characterized the distinct expression profile and prognostic values of MUC4 in pan-cancer." (PMID 34336844, 2021). "MiRnome analysis comparing MUC4-KD versus Mock cancer cells showed that MUC4 inhibition impaired miR-210-3p expression." (PMID 34944818, 2021). "In conclusion, our findings suggested the necessity to more carefully evaluate MUC4 as a biomarker and therapeutic target and develop the new antibodies for cancer detection and intervention." (PMID 34336844, 2021). "MUC4 is also aberrantly overexpressed in various epithelial malignancies and functionally contributes to cancer development and progression." (PMID 34887447, 2021). "Based on these results, we further studied the correlation of MUC4 alteration with prognosis in top five cancer types and found the prognostic value of MUC4 alteration." (PMID 34336844, 2021). "MUC4 was negatively enriched in four cancer types, including KIRP (NES = −1.806, FDR = 0.2136), HNSC (NES = −1.683, FDR = 0.205), SARC (NES = −1.934, FDR = 0.0849), and GBM (NES = −1.828, FDR = 0.026)." (PMID 34336844, 2021). "Overexpressed MUC1 and MUC4 on the surfaces of cancer cells provide steric hindrance for the conjugation between cancer cells and cytotoxic lymphocytes, resulting in a decreased cancer cell lysis." (PMID 34681277, 2021).
cancer (continued). "AFP can bind to MUC1 and MUC4 to synergistically promote cancer cells proliferation, migration and invasion." (PMID 33718192, 2021). "To further understand the relevance of MUC4 expression in cancer, we used the TCGA database to study the relationship between MUC4 expression and pathological stage via GEPIA2." (PMID 34336844, 2021). "Our results revealed that MUC4 expression is upregulated or downregulated in different types of cancer." (PMID 34336844, 2021). "MiR-150 inhibits growth and malignant behavior of cancer cells by binding to 3′UTR of Mucin 4 (MUC4), a high molecular mass proteoglycan, and down-regulates its expression." (PMID 33849540, 2021). "MUC4 mRNA in cancer cells is stabilized by Gal-3, which is found in the structure of hnRNP-L-containing RNA granules." (PMID 34604242, 2021). "We depicted global alterations and epigenetic regulation of MUC4 across multiple cancer types, which showed that genomic alteration was an unfavorable factor for overall survival in LUSC and UCEC." (PMID 34336844, 2021). "In contrast, MUC4 was positively enriched in three cancer types, including THCA (NES = 1.774, FDR = 0.0845), PRAD (NES = 1.638, FDR = 0.0585), and THYM (NES = 1.743, FDR = 0.0804)." (PMID 34336844, 2021). "MUC1 and MUC4 induced by IL-17RB upregulate expression of cancer stemness-related genes, such as SOX2, Nanog, Oct-4, and surface CD44 to facilitate sphere formation." (PMID 33082357, 2020). "MUC4 is aberrantly expressed in a variety of cancers, including breast tumors, and in this setting it can also induce phosphorylation of HER2, which results in inactivation of the pro-apoptotic pathway and in stimulation of pro-survival proteins." (PMID 32391269, 2020). "In this work, we found IL-17RB upregulates MUC1 and MUC4 through NF-κB pathway to confer cancer cells resistance to gemcitabine." (PMID 33082357, 2020). "In order to clarify the role of MUC4 in the bile-induced cancer progression, we down-regulated MUC4 by siRNA transfection and found that MUC4 act as an oncogenic mucin." (PMID 33328627, 2020). "The IHC findings of the present study confirm those of previous studies that reported increased MUC4 expression in cancer tissue compared to normal tissue." (PMID 32701958, 2020). "MUC4 protects cancer cells during hematological transmission and promotes the invasion and colonization of cancer cells to metastatic sites." (PMID 31915505, 2019). "MUC4 has been reported to promote cancer progression involving EMT in a variety of epithelial carcinomas." (PMID 30683132, 2019). "Recent studies have shown that MUC4 promotes cancer progression involving EMT in various human cancers, such as cervical cancer, ovarian cancer, pancreatic cancer and breast cancer." (PMID 30683132, 2019). "MUC1, MUC2, MUC4, and MUC16 are mucins associated with cancer progression, whereas MUC16 is also used for cancer diagnostics." (PMID 31552050, 2019). "Further, due to its aberrant glycosylation and extensive splicing, MUC4 is a potential target for cancer immunotherapy." (PMID 31258832, 2019). "This technological approach will be very useful in the future to validate small molecule binding affinities targeting MUC4-ErbB2 complex for drug discovery development in cancer." (PMID 31723153, 2019). "Conversely, to investigate the effect of TTP depletion on MUC4 expression, cancer cells were transformed with scRNA and siTTP." (PMID 31141941, 2019). "At the cancer cell surface MUC4 interacts with ErbB2 receptor via EGF domains to promote cell proliferation and migration." (PMID 31723153, 2019). "MUC4 is a membrane-bound mucin protein that plays a role in migration and invasion of cancer cells, and serves as a sensor for a variety of downstream cell signaling pathways." (PMID 31141941, 2019). "PKC-mediated activation of MUC4 has been suggested as another pathway by which growth factors increase MUC4 expression in cancer cells." (PMID 31514468, 2019).
cancer (continued). "Overexpression of MUC4 (mucin 4), a transmembrane mucin, has been observed frequently in several cancers, including PDAC." (PMID 30866526, 2019). "Altogether, this study provides the link between (i) MUC4 expression and clinical outcome in cancer and (ii) MUC4 expression and correlated genes involved in cell adhesion, cell–cell junctions, glycosylation and cell signaling." (PMID 30236127, 2018). "Logistic regression was performed to predict expression of MUC4 protein in cancer and cysts, by type of cysts." (PMID 34164227, 2018). "Among MUC family, MUC16 and MUC4 were the top two RMGs identified from most cancer types (17 and 12, respectively)." (PMID 30107644, 2018). "Using cBioportal or SurvExpress tools, we studied MUC4 expression in large-scale genomic public datasets of human cancer (the cancer genome atlas, TCGA) and cancer cell line encyclopedia (CCLE)." (PMID 30236127, 2018). "We mainly observed an important z-score expression of MUC4 in carcinoma samples (n = 538 samples, p = 0.001)." (PMID 30236127, 2018). "MUC4 is a membrane-bound mucin that promotes carcinogenetic progression and is often proposed as a promising biomarker for various carcinomas." (PMID 30236127, 2018). "Further, MUC-4—a transmembrane protein—expression has been observed in pancreatic ductal adenocarcinoma, and it is aberrantly glycosylated, which is involved in cancer progression and neoplast cancer aggression." (PMID 29068423, 2017). "Based on these insights, we developed an outline of the processes and mechanisms by which MUC4 critically supports the propagation and survival of cancer cells in various epithelial organs." (PMID 27829225, 2017). "In both low- and high-grade forms of these cancers, MUC4 expression is correlated with an increased survival rate and a reduced recurrence rate." (PMID 27829225, 2017). "It has been demonstrated that mucins such as MUC4 and MUC13 are associated with cancer development; the circulating level of MUC16 is even used to monitor patients with ovarian cancer." (PMID 29062084, 2017). "One recent study reported cancer-associated autoantibodies against a set of aberrantly glycosylated glycopeptides derived from mucin MUC1 and MUC4 in sera of CRC patients." (PMID 27705923, 2017). "Another interesting observation is that, in three out of six cancer sets, the gene most frequently involved with FPVs was MUC4." (PMID 28659176, 2017). "The distribution of MUC4 changes in the stratified epithelium, and its expression is aberrant in cancers of the upper aerodigestive tract." (PMID 27829225, 2017). "Cancer stem cells and MUC4 contribute to cancer relapse and progression by assisting in the initiation, growth, and recurrence of various carcinomas." (PMID 27829225, 2017). "In any cancer, oxidative stress induced by hypoxia, was reported to promote oncogenic protein (MUC4) degradation via autophagy, enhancing the survival of cancer cells in the pancreas." (PMID 28959211, 2017). "MUC4 relatively shows high levels of methylation in normal tissue, which is especially evident in cancer." (PMID 28978023, 2017). "MUC4 expression has an inverse relationship with the survival rates of epithelial carcinoma patients." (PMID 27829225, 2017). "This is in contrast to the majority of forms of epithelial carcinoma, which show abnormally high rates of MUC4 expression that increase with disease progression." (PMID 27829225, 2017). "The multiple cellular functions directed by the sequence, structure, and glycosylation of MUC4 suggest it promotes the progression of various forms of epithelial carcinoma." (PMID 27829225, 2017). "The specific and aberrant patterns of MUC4 expression during the progressive stages of various forms of epithelial carcinoma implicate MUC4 as a novel potential biomarker and therapeutic target." (PMID 27829225, 2017).